PIK3CA (phosphatidylinositol-4,5-bisphosphate 3-kinase catalytic subunit alpha)
Diseases named in the same sentence as PIK3CA in open-access papers (continued):
Sharing a sentence is not in itself a finding about the gene and the disease.
breast cancer (continued). "In addition to this, there had been significant progress in understanding the molecular mechanisms underlying the development and progression of TNBC, as well as in developing new drugs for patients with PIK3CA-mutated breast cancer." (PMID 38894873, 2024). "In breast cancer, mutations in PIK3CA also have prognostic relevance and are associated with better invasive disease-free survival (HR: 0.77; p < 0.001), with evidence for a more substantial effect in the first 5 years (0 to 5 years: HR: 0.73; p < 0.001; 5 to 10 years: HR: 0.82; p = 0.037)." (PMID 39768623, 2024). "In addition, mutations of the PIK3CA gene are potential pharmacological targets of aromatase-inhibitor resistant breast cancers." (PMID 39323992, 2024). "The PIK3CA (H1047R) mutation has been correlated with poor clinical prognosis not only in gastric carcinoma, glioblastoma, and colorectal carcinoma but also in breast cancer." (PMID 38279318, 2024). "However, ≃ 40% of patients with HR + /HER2 − breast cancer have mutations in the PIK3CA gene, which can lead to resistance to endocrine-based therapy and eventual disease progression or relapse over time." (PMID 39177931, 2024). "Finally, in breast cancer, 9 out of 213 cases (4.05%) with multiple PIK3CA mutations had PTEN mutations compared with 7 out of 70 cases (10.00%) with a single mutation." (PMID 39054873, 2024). "Recently, EVs derived from cancer cells were shown to reduce the apoptosis rate via upregulation of BCL2 in other cancer cells, and tumor-derived EVs containing extracellular matrix molecules induced mutations in PIK3CA, which promoted proliferation and invasion in breast cancer." (PMID 39474419, 2024). "Mutations in PIK3CA E545K are frequent oncogenes, particularly in breast cancer." (PMID 39354592, 2024). "In addition, metastatic breast cancer samples were more likely to have a KIT or PIK3CA mutation compared to primary breast cancer samples." (PMID 38927753, 2024). "The frequency of PIK3CA mutations in relapsed endocrine-resistant breast cancer and how these may fluctuate compared to primary tumors is unknown." (PMID 38822093, 2024). "Our study highlights the potential importance of determining PIK3CA mutational status in early breast cancer, especially in research stetting, and by that indicates the need for further research regarding the use of PIK3CA inhibitors in the neo/adjuvant treatment strategy." (PMID 39742376, 2024). "It is also being investigated in combination with trastuzumab with or without fulvestrant compared to trastuzumab plus chemotherapy in previously treated patients with PIK3CA-mutated HER2-positive advanced breast cancer in phase III ALPHABET trial (NCT05063786)." (PMID 38396649, 2024). "However, PIK3CA mutations were associated with a lower pathological complete response in HER2-positive breast cancer treated with anti-HER2 therapy." (PMID 39768623, 2024). "Potentially actionable molecular alterations include agnostic targets (NTRK1-2-3, RET fusions, BRAF V600E mutations, microsatellite instability, high tumor mutational burden), or tissue-specific targets, such as EGFR mutation in NSCLC or PIK3CA mutations in breast cancer." (PMID 39766151, 2024). "However, another study found alpelisib exerted stronger anti-tumour effects on canine mammary tumour cell lines with PIK3CA mutations than on the wild-type cell lines." (PMID 38787171, 2024). "Reported mutation rates for PIK3CA in breast cancer range from 18% to 40%." (PMID 39329702, 2024). "MTORC1 signaling has been supported in a previous study where PIK3CA mutations are associated with gene signature of low MTORC1 signaling in estrogen receptor-positive breast cancer, and PIK3CA mutations are one of the most common genetic aberrations in breast cancer." (PMID 38673997, 2024).
breast cancer (continued). "Next, two MGPs, “phosphoenolpyruvate-PIK3CA-glycolysis/gluconeogenesis” and “fumarate-PIK3CA-citric acid cycle,” were predicted for Breast-AdenoCA, and may provide hypotheses for overcoming trastuzumab resistance in breast cancer with PIK3CA mutation." (PMID 38468344, 2024). "PIK3CA mutation is reported highly represented in ER + /HER2- breast cancer." (PMID 38243340, 2024). "RNMT is a promising therapeutic target in PIK3CA (phosphatidylinositol-4,5- bisphosphate 3-kinase catalytic subunit alpha gene) mutant breast cancer, as PIK3CA mutations in breast cells depend on RNMT (mRNA cap methylation) for their survival and proliferation." (PMID 38402266, 2024). "Our results may help further investigations of PIK3CA mutational status in patients with endocrine-resistant breast cancer, which can aid in optimizing their treatment and subsequent assessment." (PMID 38822093, 2024). "MAPK3’s involvement in cell proliferation and survival, alongside PIK3CA and mTOR’s roles in metabolic regulation and tumor progression, underlines their contribution to breast cancer pathophysiology, particularly in aggressive subtypes like TNBC and HER2-positive cancers." (PMID 39850811, 2024). "Furthermore, when the PIK3CA mutations identified using the opposite tumor as a normal were examined, all mutations were found to be common breast cancer hotspots as identified by COSMIC." (PMID 38722955, 2024). "Like human breast cancer, PIK3CA mutations occur frequently in canine mammary tumors." (PMID 38807154, 2024). "Its combination with tamoxifen in the phase II PIKTAM trial in HR-positive, HER2-negative advanced breast cancer patients was terminated early due to its risk-benefit profile despite its promising efficacy in the PIK3CA-mutated group with a median PFS of 8.7 months, ORR of 40%, and DCR of 80%." (PMID 38396649, 2024). "Similarly, the vast majority of patients benefiting from genomically-tailored therapy in a recently reported breast cancer trial either had a PIK3CA mutation and received alpelisib, or had BRCA1/2 or similar alterations and received olaparib." (PMID 38612902, 2024). "Furthermore, AKT inhibitors like capivasertib are undergoing rigorous investigation for their efficacy against breast cancers with specific genetic aberrations such as PIK3CA mutations or the AKT1E17K mutation." (PMID 39199633, 2024). "Alpelisib has been recommended for breast cancer patients carrying PIK3CA mutations." (PMID 38310289, 2024). "We next assessed whether PIK3CA mutations predicted AKT activation in 29 breast cancer cell lines retreated from the publicly available DepMap portal." (PMID 39322687, 2024). "Based on our previous work, we hypothesized that arachidonic acid would be elevated in breast cancer tissue harboring PIK3CA mutations." (PMID 39294437, 2024). "Furthermore, hormone receptor status, namely ER receptor positivity, is linked to the possible effectiveness of PI3K inhibitors in ER+ breast cancer since PIK3CA mutations are more prevalent in this subtype." (PMID 39770406, 2024). "Among them, PIK3CA E542K mutations are the most representative, and accurate detection of PIK3CA E542K mutations may significantly advance the accurate diagnosis and treatment of breast cancer development." (PMID 38257640, 2024). "One of the frequently occurring mutations in canine mammary tumors is the PIK3CA mutation." (PMID 38807154, 2024). "According to cBioPortal analysis of published cancer genomics datasets such as The Cancer Genome Atlas4, breast cancer is frequently characterized by genetic alterations of PIK3CA (~35–45%, mostly activating mutations) and PTEN (~6–10%, mostly inactivating mutations or deletions)." (PMID 38839777, 2024).
breast cancer (continued). "PIK3CA mutations occur in approximately 8% of cancers, including 40% of HR-positive breast cancers." (PMID 39493752, 2024). "Hotspots (HS) mutations in the PIK3CA gene may lead to poorer oncological outcomes and endocrine resistance in advanced breast cancer (BC), but their prognostic role in early‐stage disease remains controversial." (PMID 39235099, 2024). "Breast cancer frequently harbours mutations in the kinase PIK3CA." (PMID 37711177, 2023). "The relationship between PIK3CA mutations and prognosis in breast cancer patients is controversial." (PMID 37106324, 2023). "Thus, an overview of the healthcare landscape of PIK3CA mutation testing in breast cancer on tissue and LB material using molecular pathology methods in the German-speaking regions was obtained." (PMID 36367572, 2023). "This study evaluated the frequency of PIK3CA mutations in the Taiwanese breast cancer population." (PMID 37655108, 2023). "CDH1 and PIK3CA mutation relate to metastasis in breast cancer patients." (PMID 37426414, 2023). "Given the similarity between canine and human breast cancers, the cell lines established in this study could be useful for the development of new drugs targeting PIK3CA mutation-derived human breast cancer." (PMID 38033642, 2023). "The effect was stronger in HCC1954 cells that contain the PIK3CA H1047R activating mutation shown to be associated with decreased pathological complete response in HER2 breast cancer patients treated with combined trastuzumab and lapatinib and increased resistance to HER2-targeting drugs." (PMID 36670508, 2023). "The frequency of PIK3CA mutations varied by breast cancer subtype and menopausal status." (PMID 37655108, 2023). "Moreover, MEN1611 selectively decreased the p110α protein levels in PIK3CA mutated breast cancer cells in a concentration- and proteasome-dependent manner." (PMID 36913051, 2023). "PIK3CA is one of the most frequently mutated genes in breast cancer." (PMID 37965796, 2023). "Furthermore, with the rise of targeted therapy, it is critically important to identify the characteristics of PIK3CA mutations in US images of breast cancer." (PMID 38025526, 2023). "This was suggested by the high frequency of GOF PIK3CA mutations in breast cancer cases." (PMID 37109059, 2023). "The study also reported that acini harboring oncogenic PIK3CA H1047R mutation, frequently mutated in breast cancer and leading to constitutive activation of the PI3K pathway, display increased ERK frequency with inner cell survival and absence of lumen formation." (PMID 38033496, 2023). "This cohort study assesses whether PIK3CA mutations among patients with ERBB2/HER2-positive early breast cancer are associated with treatment response and outcome, and if these associations vary by hormone receptor status or intrinsic molecular subtype." (PMID 38117494, 2023). "In addition to the importance of PIK3CA mutations in human breast cancer, various studies have shed light on their correlation with canine tumors." (PMID 38033642, 2023). "We suggest that activation of the KRAS or PIK3CA oncogenes or loss of the PTEN suppressor gene may be important for mammary tumor development in dogs." (PMID 36635367, 2023). "Moreover, breast cancer was associated with a high treatment recommendation rate (29%), but 50% of cases involved PIK3CA mutation for a clinical trial of the PIK3CA inhibitor." (PMID 36251535, 2023). "Finally, our results in Breast-AdenoCA also highlighted some genes that are specifically known to be frequently mutated in breast cancer, including PIK3CA, CDH1, GATA3, and MAP2K4." (PMID 38062391, 2023).
breast cancer (continued). "The most common mutations in breast cancer are located in the helical (exon 9) and kinase (exon 20) domains, with the hotspots being E545K, E542K, and H1047R, accounting for approximately 80% of all PIK3CA mutations." (PMID 37176102, 2023). "Together, these results demonstrate that the FBXO3-USP4-Twist1 axis is critically important in p110αH1047R-induced cell migration and tumor metastasis, and that elevated expression of PIK3CA/FBXO3/USP4/Twist1 is associated with poor clinical outcomes of breast cancer patients." (PMID 38134227, 2023). "PIK3CA mutations may be associated with outcomes of patients with ERBB2/HER2-positive early breast cancer (EBC)." (PMID 38117494, 2023). "PIK3CA, the gene encoding the p110α catalytic subunit of PI3Kα, is mutated in 20–40% of breast cancers, and most frequently in estrogen receptor-positive (ER+) breast cancers." (PMID 37471270, 2023). "NCCN guidelines (2019) recommend PIK3CA mutation tests for patients with ER+/HER2- breast cancer." (PMID 36959802, 2023). "Based on the high prevalence of PIK3CA mutation, reaching 50%, in endometrial cancer, we preclinically investigated the effectiveness of a combination of a PI3K inhibitor with eribulin, a post-paclitaxel therapy for breast cancer, in treating paclitaxel-resistant, PIK3CA-mutated endometrial cancer." (PMID 37835582, 2023). "Association between PIK3CA mutations and clinicopathological characteristics of breast cancer." (PMID 37195967, 2023). "PIK3CA mutations occur in nearly 40% of patients with HR+/HER2- breast cancer." (PMID 37251941, 2023). "Most PIK3CA-mutant or PTEN-deficient breast cancer cell lines are highly sensitive to MK-2206." (PMID 36671478, 2023). "We further analyzed the characteristics of VCLs, such as their cell morphology, growth rate, and gene expression, to investigate whether the PIK3CA mutation status is related to the features of canine mammary tumors." (PMID 38033642, 2023). "For contemporary breast cancer actionability, PIK3CA mutation is a biomarker for the FDA-approved PI3Kα inhibitor alpelisib, AKT1 mutation is indicated for agents such as capivasertib (AZD5363) and ipatasertib, and ERBB2 mutation for tyrosine kinase inhibitor neratinib." (PMID 37760445, 2023). "Indeed, PIK3CA is one of the most commonly mutated genes, with a rate of about 30% in breast cancer." (PMID 36959802, 2023). "Recent studies demonstrated that ER+/HER2-breast cancer patients may be more likely to develop CNS metastasis if they have PIK3CA-activating mutations." (PMID 37096065, 2023). "Therefore, data from the GENIE-Project (Genomics Evidence Neoplasia Information Exchange) of the American Association for Cancer Research (AACR) showing that PIK3CA is the most frequent mutated gene in HR+/HER2-breast cancer patients, are very promising." (PMID 36367572, 2023). "Meanwhile, PIK3CA mutation is one of the most common mutations in solid tumors, especially in endometrial (42–55%); PIK3CA mutation is one of the most common mutations in solid tumors, especially in endometrial (42–55%), cervical (42%), breast cancer (27–36%)." (PMID 37583914, 2023). "Up to 40% of luminal breast cancer patients carry activating mutations in the PIK3CA gene." (PMID 38017109, 2023). "It suggests that in luminal breast cancer with a PIK3CA mutation, MAPK1/3 phosphorylation may play a critical role as a downstream effector worth targeting." (PMID 38034788, 2023). "Complete suppression of mTORC1 by RMC-6272 causes apoptosis in ER+/HER2− breast cancer cell lines, particularly in those that harbor mutations in PIK3CA or PTEN, due to inhibition of the rapamycin resistant, mTORC1 substrate 4EBP1 and reduction of the pro-survival protein MCL1." (PMID 37264081, 2023). "In addition, we lacked a comparison between in-house testing and CGP for KRAS/G12C, RET mutations, and NTRK rearrangements in NSCLC; and for PIK3CA mutations in breast cancer." (PMID 36832270, 2023).
breast cancer (continued). "Given the findings of this phase III trial, the FDA approved alpelisib plus fulvestrant in May 2019 for patients suffering from HR+/HER2- advanced breast cancer with PIK3CA mutations." (PMID 37489050, 2023). "In the phase III CLEOPATRA study, patients with HER2 + advanced breast cancer and the PIK3CA activating mutations had a worse prognosis versus patients with HER2 +/PIK3CA wild-type tumors, regardless of the anti-HER2 treatment administered (trastuzumab or trastuzumab + pertuzumab)." (PMID 37469415, 2023). "The prognostic role of PIK3CA mutations in breast cancer is equivocal, however a meta-analysis performed on PIK3CA mutation status in human breast cancer showed that mutations in this gene represented an independent negative prognostic factor with a hazard ratio of 1.6737." (PMID 36635367, 2023). "In addition, biomarker analysis from the CLEOPATRA trial showed that PIK3CA mutations were associated with worse survival outcomes in patients with advanced HER2+ breast cancer." (PMID 35800378, 2022). "Instead, our findings of a prospective well-defined homogenous cohort of early-stage breast cancer patients provide new insights to the realistic frequency of PIK3CA-mutations overall and in subgroups, as well as their association with recurrence-free interval and overall survival." (PMID 36279023, 2022). "A number of studies have shown that ctDNA PIK3CA mutations can be detected in breast cancer." (PMID 35565189, 2022). "The p110α isoform is encoded by PIK3CA, the most frequently mutated gene in breast cancers." (PMID 35053443, 2022). "However, in our study we found a significant predictive value of PIK3CA-mutations in luminal breast cancer by observing more disease-related events in patients with PIK3CA-mutations." (PMID 36279023, 2022). "A similar concordance level was observed for advanced breast cancer patients, where an overall concordance of up to 95% (negative and positive) was observed for the detection of mutations from the four major driver genes of breast cancer—PIK3CA, ESR1, AKT1, and HER2." (PMID 35805046, 2022). "This cohort study speficies the overall mutation rate of PIK3CA in early breast cancer." (PMID 36279023, 2022). "For breast cancer with PIK3CA mutations and urothelial cancer with FGFR3 translocations/mutations, the Food and Drug Administration (FDA) has approved phosphoinositide 3-kinases (PI3K) and fibroblast growth factor receptor (FGFR) inhibitors, respectively, for clinical use." (PMID 36612094, 2022). "Therefore, it is used in cancers with PIK3CA mutations, in particular uterine serous carcinomas and breast cancers, which are accompanied by hormone receptor changes because of the cross-talk between estrogen receptor (ER) and PI3K." (PMID 35785151, 2022). "Based on these results, it is recommended in the NCCN guidelines that for postmenopausal HR‐positive/HER2‐negative breast cancer patients with PIK3CA mutation, the second‐line treatment of choice should be a combination therapy of alpelisib and fulvestrant (category 1)." (PMID 38089455, 2022). "In this report, based on the consensus of 14 oncologists and seven endocrinologists, we provide guidance for hyperglycemia management strategies before, during, and after alpelisib therapy for HR+, HER2–, PIK3CA-mutated breast cancer, with a focus on a proactive, multidisciplinary approach." (PMID 35406370, 2022). "For example, the most commonly mutated gene in breast cancer is PIK3CA (36%), however, when we look at the frequency of different subtypes, PIK3CA mutation is found in 37% of luminal subtypes/ER+ tumours (45% in Luminal A, 29% in Luminal B) vs 9% of basal/ER- tumours." (PMID 35109903, 2022). "PIK3CA mutations are present in about 20% of HER2 + breast cancers." (PMID 35142964, 2022).